ENSG00000285645 (Novel protein)
Gene: Protein-coding gene on chromosome 9 (35,812,960 to 35,828,732, reverse strand). Ensembl gene ENSG00000285645.
Genetic constraint (gnomAD): Missense variants: 95 observed, 100.51 expected, observed/expected ratio (o/e) 0.95, 90% interval 0.8 to 1.12. Synonymous variants: 29 observed, 32.16 expected, observed/expected ratio (o/e) 0.9, 90% interval 0.67 to 1.23.